KPNA4 (karyopherin subunit alpha 4)
Description:
Functions in nuclear protein import as an adapter protein for nuclear receptor KPNB1. Binds specifically and directly to substrates containing either a simple or bipartite NLS motif. Docking of the importin/substrate complex to the nuclear pore complex (NPC) is mediated by KPNB1 through binding to nucleoporin FxFG repeats and the complex is subsequently translocated through the pore by an energy requiring, Ran-dependent mechanism. At the nucleoplasmic side of the NPC, Ran binds to importin-beta and the three components separate and importin-alpha and -beta are re-exported from the nucleus to the cytoplasm where GTP hydrolysis releases Ran from importin. The directionality of nuclear import is thought to be conferred by an asymmetric distribution of the GTP- and GDP-bound forms of Ran between the cytoplasm and nucleus. Mediates nuclear import of AARS1, MRTFA and RANBP3. (Microbial infection) In vitro, mediates the nuclear import of human cytomegalovirus UL84 by recognizing a non-classical NLS. In vitro, mediates the nuclear import of human cytomegalovirus UL84 by recognizing a non-classical NLS.
Synonyms: Qip1; SRP3; IPOA3; MGC12217; MGC26703
Tractability: PROTAC: ubiquitination databases record sites on it; its protein half-life has been measured.
Gene: Protein-coding gene on chromosome 3 (160,495,007 to 160,565,587, reverse strand). Ensembl gene ENSG00000186432.
Subcellular location: Cytoplasm; Nucleus
Subcellular location (Human Protein Atlas): Nucleoplasm; Nuclear membrane
Pathways (Reactome):
Disease: Maturation of DENV proteins; NS1 Mediated Effects on Host Pathways
Immune System: ISG15 antiviral mechanism
Gene Ontology:
Molecular function: nuclear import signal receptor activity; nucleocytoplasmic carrier activity; protein binding
Biological process: NLS-bearing protein import into nucleus; protein import into nucleus
Cellular component: cytoplasm; NLS-dependent protein nuclear import complex; nucleoplasm; cytosol; nuclear pore; nucleus
Genetic constraint (gnomAD): Loss-of-function variants: 2 observed, 21.17 expected, observed/expected ratio (o/e) 0.0945, 90% interval 0.038 to 0.3. The upper end of that interval is the gene's LOEUF score, 0.3, which puts it in group 1 of 6, group 1 being the genes least tolerant of losing a copy. Missense variants: 166 observed, 259.26 expected, observed/expected ratio (o/e) 0.64, 90% interval 0.56 to 0.73. Synonymous variants: 85 observed, 81.68 expected, observed/expected ratio (o/e) 1.04, 90% interval 0.87 to 1.25.
Homologues: Orthologues: chimpanzee KPNA4 (100% identical), pig KPNA4 (99% identical), mouse Kpna4 (99% identical), rat Kpna4 (99% identical), guinea pig KPNA4 (97% identical), zebrafish kpna4 (95% identical), rabbit KPNA4 (95% identical), tropical clawed frog kpna4 (95% identical), macaque KPNA4 (94% identical), dog KPNA4 (90% identical), Drosophila melanogaster Kap-alpha3 (66% identical), Caenorhabditis elegans ima-3 (63% identical), and 1 more. Paralogues in human: KPNA3 (86% identical), KPNA2 (52% identical), KPNA5 (48% identical), KPNA6 (48% identical), KPNA1 (47% identical), KPNA7 (43% identical).
Diseases named in the same sentence as KPNA4 in open-access papers:
KPNA4 is named in the same sentence as 40 diseases in open-access papers, as found by Europe PMC text mining. Sharing a sentence is not in itself a finding about the gene and the disease. The quoted sentences say what the papers report.
prostate carcinoma (10 papers, 2017 to 2023). A carcinoma that arises from epithelial cells of the prostate gland. "For example, it has been reported that KPNA4 is closely associated with prostate cancer metastasis." (PMID 33535183, 2021). "Beyond the direct effect of KPNA4 suppression on prostate cancer cell growth, KPNA4 knockdown reduced M2 tumor-associated macrophage (TAM) infiltration into tumors in vivo by reducing chemokine (C-C motif) ligand 2 (CCL2) and chemokine (C-C motif) ligand 8 (CCL8) expression in prostate tumor cells." (PMID 29050362, 2017). "The expression of KPNA4 in prostate cancer was shown to promote metastasis through miR-708-KPNA4-TNF axes, and KPNA4 was found to enhance cancer cell proliferation and cisplatin resistance in cutaneous squamous cell carcinoma." (PMID 35991543, 2022). "Recent studies have shown that inhibition of KPNA4 attenuates prostate cancer metastasis and that KPNA4 participates in the proliferation of cutaneous squamous cell carcinoma." (PMID 33535183, 2021). "This profound role of KPNA4 in prostate cancer makes the use of miR-708-5p as a therapeutic enticing." (PMID 29050362, 2017). "Karyopherin subunit alpha 4 (KPNA4), which is a member of the nuclear transport factors KPNA family, has been reported to be associated with multiple cancers, including prostate cancer, hepatocellular carcinoma, lung cancer, ovarian cancer, glioblastoma and other malignancies." (PMID 35425701, 2022). "Moreover, it has been shown that KPNA4 regulates the development of prostate cancer, glioblastoma and cutaneous squamous cell carcinoma." (PMID 34930332, 2021). "It was reported that inhibiting KPNA4 attenuated prostate cancer metastasis." (PMID 33327962, 2020). "Importantly, the expression amounts of KPNA2 was comparable between HNSCC and prostate cancers, whereas KPNA4 is most abundant in HNSCC." (PMID 31822798, 2020). "KPNA4 acts as an activator of NF-κB signaling, which stimulates cancer cell proliferation and invasion and creates a proinflammatory tumor microenvironment that favors prostate cancer metastasis." (PMID 31287002, 2019). "It would be worthwhile to investigate whether miR-708-5p treatments would replicate the KPNA4 knockdown results, as it would solidify a novel class of therapeutics in prostate cancer." (PMID 29050362, 2017). "The anti-tumorigenic role of miR-708-5p in prostate cancer was not solely due to CD44, as miR-708-5p also targets RAC-beta serine/threonine-protein kinase (AKT2), NNAT, and karyopherin importin subunit alpha-4 (KPNA4) in prostate cancer." (PMID 29050362, 2017).
breast carcinoma (8 papers, 2014 to 2023). "We demonstrated that Hsa-miR-567 expression is significantly downregulated in poor prognosis breast cancer, compared to better prognosis breast cancer, having a role in the control of cell proliferation and migration by regulating KPNA4 gene." (PMID 28000015, 2017). "Moreover, a meta-analysis showed that a downsized four-gene signature, consisting of DDX19A, FOXM1, KPNA4, and H2AFV, represents a highly significant finding for the biology underlying histological grades in breast cancer, in particular, regarding cell proliferation, and DNA stability." (PMID 33968728, 2021). "The association of the six top-ranked karyopherins (KPNA2, XPOT, CSEL1, KPNA1, KPNA4, and TNPO1) in the breast cancer datasets from Oncomine was analyzed using a Kaplan-Meier Plotter." (PMID 37928256, 2023). "Here we show that overexpression of TDP-43 reduced NF-κB activity in human breast cancer MCF-7 cells and we further report that TDP-43 prevents the nuclear transportation of p65 by competing for importin alpha 3 (KPNA4)." (PMID 26571498, 2015). "Consistently, we found that karyopherin 4 (KPNA4), predicted target gene of Hsa-miR-567 as identified by our in silico analysis, is upregulated in highly aggressive MDA-MB-231 breast cancer cell line and patient tissues with poor prognosis with respect to good prognosis." (PMID 28000015, 2017). "In breast cancer, miR-567 could inhibit cancer cell proliferation and migration by regulating KPNA4; miR-567 could also regulate autophagy and reverse trastuzumab resistance via ATG5 in breast cancer; in renal cell carcinoma, miR-567 could inhibit cancer cells progression by regulating PRDX3." (PMID 34226531, 2021).
glioblastoma (7 papers, 2015 to 2022). The most malignant astrocytic tumor (WHO grade IV). "Increased miR-181 s reverses EMT via decreasing KPNA4 in glioblastoma." (PMID 32943995, 2020). "They had been observed in glioblastoma, which could reverse mesenchymal transition by targeting KPNA4." (PMID 29382357, 2018). "It was reported that KPNA4 is a direct target and antagonizes the EMT-inhibiting effect of miR-181b-5p in glioblastoma." (PMID 33327962, 2020). "miR-181b-5p targets the KPNA4 gene to inhibit EMT progression, and impede invasion and proliferation capacity of glioblastoma cells." (PMID 33680908, 2020).
cutaneous squamous cell carcinoma (5 papers, 2021 to 2025). "For example, high expression of KPNA4 in cutaneous squamous cell carcinoma was discovered to enhance cancer cell proliferation as well as cisplatin resistance." (PMID 35991543, 2022). "In cutaneous squamous cell carcinoma, KPNA4 has been shown to promote cancer cell proliferation and cisplatin resistance." (PMID 33535183, 2021).
glioma (4 papers, 2015 to 2021). A benign or malignant brain and spinal cord tumor that arises from glial cells (astrocytes, oligodendrocytes, ependymal cells). "The pathway analyses indicated that miR-181b inhibited EMT by blocking KPNA4 expression, which limited glioma growth in vitro and in vivo." (PMID 26283154, 2015). "miR-181 can also inhibit malignant transformation of gliomas by targeting KPNA4." (PMID 33348707, 2020). "KPNA4 protein expression in glioma tissues was analyzed by immunohistochemistry (IHC) to determine whether it correlated with reduced miR-181b expression." (PMID 26283154, 2015).
hepatocellular carcinoma (3 papers, 2021 to 2023). A malignant tumor that arises from hepatocytes. "Moreover, KPNA4 was found to be correlated with immune cell infiltration in hepatocellular carcinoma, suggesting that KPNA4 expression may have an effect on TME and anti-tumor immunity." (PMID 35425701, 2022). "According to a recent study, high-expressed KPNA4 in hepatocellular carcinoma (HCC) can indicate poor survival outcome, supporting KPNA4 as an independent predictor of HCC prognosis." (PMID 35425701, 2022).
lung adenocarcinoma (3 papers, 2020 to 2024). A carcinoma that arises from the lung and is characterized by the presence of malignant glandular epithelial cells. "Therefore, aiming at ST7-AS1 and KPNA4 or upregulation of Mir-181B-5p may be beneficial for the treating lung adenocarcinoma." (PMID 36276269, 2022).
lung carcinoma (3 papers, 2020 to 2022). "Regulating upstream modulators facilitates angiogenesis as well as progression in lung cancer by targeting the miR‐340‐5p/KPNA4 axis." (PMID 35991543, 2022). "YY1 has been reported to induce lncRNA MCM3AP-AS1 overexpression in lung cancer, and overexpressed MCM3AP-AS1 promoted angiogenesis via targeting KPNA4 through shared miR-340-5p." (PMID 32272940, 2020).
frontotemporal dementia (2 papers, 2018 to 2025). Frontotemporal dementia (FTD) comprises a group of neurodegenerative disorders, characterized by progressive changes in behavior, executive dysfunction and language impairment, as a result of degeneration of the medial prefrontal and frontoinsular cortices. "Together with earlier reports, our findings establish KPNA4 abnormalities as a molecular signature of TDP-43 proteinopathies and identify it as a potential therapeutic target to sustain nuclear TDP-43 essential for cellular homeostasis affected in ALS and frontotemporal dementia." (PMID 40772263, 2025). "Comparable KPNA4 pathology was observed in both sporadic frontotemporal dementia and C9ALS/FTD patient brains characterized by its nuclear depletion and cytosolic accumulation, irrespective of TDP-43 or dipeptide-repeat protein aggregates." (PMID 30239641, 2018).
dental caries (1 paper, 2014). The decay of a tooth, in which it becomes softened, discolored, and/or porous. "Dental caries’ GWAS identified significant signals in LYZL2, AJAp1, and KPNA4; and efforts are ongoing to identify genetic factors for multiple caries phenotypes." (PMID 24702466, 2014).
diffuse large B-cell lymphoma (1 paper, 2022). "Furthermore, KPNA4 expression was significantly elevated in many other tumors including diffuse large B cell lymphoma (DLBC), esophageal carcinoma (ESCA), lung squamous cell carcinoma (LUSC) and stomach adenocarcinoma (STAD)." (PMID 35425701, 2022).
gallbladder cancer (1 paper, 2020). "Recent studies have revealed the oncogenic role of IPO3/KPNA4 in the head and oncogenic neck squamous cell carcinomas and the potential target of KPNA2 in gallbladder cancer." (PMID 32661323, 2020).
lymph node metastasis (1 paper, 2022). "Further clinical correlation analysis demonstrated that patients with advanced stage and high histological grade tended to express higher level of KPNA4, and KPNA4 expression was also associated with tumor infiltration and lymph node metastasis." (PMID 35425701, 2022).
motor neuron diseases (1 paper, 2025). "Although much less evidence exists for an impact of the closely related paralogue KPNA4 on the development of motor neuron diseases (MND), we decided to analyse Kpna4-knockout (KO) mice in parallel, as KPNA3 and KPNA4 display a high homology and share common cargoes." (PMID 40565582, 2025).
pancreatic cancer (1 paper, 2022). "Another cohort showed that KPNA4 was also increased in pancreatic intraepithelial neoplasia, which is a precancerous lesion of pancreatic cancer." (PMID 35425701, 2022). "To experimentally validate these findings, we knocked down KPNA4 by small interfering RNA (siKPNA4) in MIA PaCa-2 and PANC-1 pancreatic cancer cell lines with high KPNA4 expression." (PMID 35425701, 2022).
proteinopathies (1 paper, 2025). "Our findings therefore establish KPNA4 as a molecular signature of ALS and FTD and suggest a gain-of- KPNA4 function as a potential therapeutic target that could sustain nuclear TDP-43 essential for cellular homeostasis and neuronal function affected in TDP-43 proteinopathies." (PMID 40772263, 2025).
tumor (13 papers, 2017 to 2024). "Altogether, these results suggest that KPNA4 expression is associated with tumor progression in PDAC patients." (PMID 35425701, 2022). "Lastly, tumor stage and grade were analyzed in HCC patients, and it can be found that increased KPNA4 mRNA expression was associated with higher tumor stage and grade." (PMID 33535183, 2021). "The results showed that tumor stage, macrophage, and dendritic cell levels, and KPNA4 expression were all significant risk factors for a poor prognosis and KPNA4 expression was an independent factor that influenced 3-year and 5-year survival rates." (PMID 33535183, 2021). "In current study, increased KPNA4 expression was significantly associated with higher tumor stage and grade." (PMID 33535183, 2021). "KPNA4 is also required for the activation of Notch signalling, which is associated with tumour recurrence as well as tumour initiation and growth." (PMID 33327962, 2020). "KPNA4 expression was associated with tumor progression in PDAC patients." (PMID 35425701, 2022). "KPNA4 exerts tumor-promoting roles in PDAC cells and is associated with the immunosuppressive TME, which may be partly mediated by FAK signaling and PD-L1 expression." (PMID 35425701, 2022). "KPNA4 is a carrier that mediates multiple transcription factors, and previous data have confirmed that the protein is associated with the localization of Notch intracellular domain, which is involved in tumor recurrence." (PMID 34930332, 2021). "Various studies have highlighted that nuclear transport receptors including XPO1, KPNA2, and KPNA4, exhibit hyperactivity in cancer and facilitate the export of vital tumor suppressors to the cytoplasm or the import of oncogenes to the nucleus." (PMID 38820302, 2024). "Our data indicate that, besides CD73, GALC transduction induces an increase in the levels of the importin karyopherin subunit alpha 4, kynureninase, and RNA-binding motif protein 12, all involved in tumor immune escape." (PMID 37445731, 2023). "Immune infiltration analysis was performed to explore the potential roles of KPNA4 in the tumor microenvironment of PDAC." (PMID 35425701, 2022). "To demonstrate the role of KPNA4 in the malignant behaviors of tumor cells, we first evaluated the transfection efficiency of siKPNA4 by qRT-PCR." (PMID 35425701, 2022). "Univariate analysis indicated that higher T stage, N stage and histological grade, larger tumor size and higher KPNA4 expression were all correlated with worse survival." (PMID 35425701, 2022). "Karyopherin subunit alpha 4 (KPNA4) is a nuclear transport factor and plays tumor-promoting roles in multiple cancers." (PMID 35425701, 2022). "Complete data from 210 patients identified in TCGA database was used to perform Cox analyses, and the results showed that KPNA4 expression, as well as age, BMI, TB level, and tumor histopathological grade were significant prognostic factors for HCC." (PMID 33535183, 2021). "Herein, we first examined the correlations of KPNA4 level and immune infiltration cells, and then detected KPNA4 expression in common human tumor tissues and normal tissues." (PMID 33535183, 2021). "Using online algorithms, we were able to predict potential miR-361 target genes involved in cancer metastasis, such as MEF2D, ROCK1 and WNT7A, and the tumor microenvironment, including KPNA4, PDE4B and VEGF-A." (PMID 31287002, 2019). "Moreover, KPNA4 was correlated with immunosuppressive cells infiltration and T cell exhaustion in the tumor microenvironment of PDAC." (PMID 35425701, 2022). "Additionally, proliferation and migration promoting functions of KPNA4 in vitro require to be verified by in vivo xenograft tumor model and metastasis model." (PMID 35425701, 2022). "KPNA4 has previously been identified as a tumor promoter gene in some cancers." (PMID 35991543, 2022).